CD80 (CD80 molecule)
Diseases named in the same sentence as CD80 in open-access papers (continued):
Sharing a sentence is not in itself a finding about the gene and the disease.
tumor (continued). "The functional consequence of this selective gain-of-function in CARD11 recruitment in mice is to correct the majority of activation and differentiation defects caused by CD28 deficiency or by the absence of the CD80 and CD86 ligands including Treg cell development and tumor eradication." (PMID 40402149, 2025). "Notably, exosomes derived from Rab27a‐overexpressing lung cancer cells not only promote upregulation of MHC class II, CD80, and CD86 on DCs, but also facilitate CD4+ T cell proliferation and type I cytokine secretion, culminating in effective tumor growth inhibition in vivo." (PMID 41256221, 2025). "Furthermore, there was no significant change in tumor cell phagocytosis or the expression of co-stimulatory markers CD80 and CD86 when compared to NDV alone." (PMID 41322194, 2025). "Blocking one inhibitory ligand (like PD-L1) might not be enough because other checkpoints (like CD80 and others) also help the tumor avoid the immune system at the same time." (PMID 41550427, 2025). "Additionally, tumor cells in these regions upregulated genes such as IL7R, CD80, and NLRC5, which are involved in T cell survival, co-stimulatory signaling, and antigen presentation, thereby supporting T cell recruitment, activation, and sustained immune responses." (PMID 41001043, 2025). "In addition, aPD-1@PMPNs promoted the activation of DCs in both tumor-draining and non-tumor-draining lymph nodes, as demonstrated by the increased CD80+CD86+ double-positive population." (PMID 40625885, 2025). "In this model, we see clear upregulation of CD80 on Bead+ monocytes in the irradiated tumor, but not on Bead+ monocytes in the non-irradiated tumor on the opposite flank (Fig. 4Cii), indicating that this is a site-specific and not a systemic effect of radiation." (PMID 41417245, 2025). "After demonstrating in vivo efficacy of our CAR/CCR construct in the treatment of CD19/CD80/CD86-positive tumors, we next raised the question whether second-line treatment with CAR (2nd Gen) or CAR/CCR T cells can increase the survival of tumor-relapsed mice after CAR T cell treatment." (PMID 38340727, 2024). "The positivity for CD80 expression was higher in patients who did not have tumor ulceration." (PMID 37614091, 2024). "One reason the immune system cannot wipe out tumors is that T cells encounter tumor antigen-derived peptides on the surface of tumor cells in a tolerant but not activating environment since tumor cells do not express T-cell costimulatory molecules such as CD80." (PMID 39575257, 2024). "However, we revealed that the internalised tumour membrane PD-L1 induced by PD-1/CD80+ sEVs did not ended in proteasome- or lysosome-mediated degradation, but mainly underwent secretion of PD-L1+ sEVs instead." (PMID 38719909, 2024). "In addition, CD80 and CD86 are also involved in anti-tumor immunity." (PMID 37614091, 2024). "As our studies have shown TGFβ-mediated upregulation of CD80 expression following the sequential passaging of tumor cells in the HS cohort, we next studied if the combination of anti-TGFβ monoclonal antibodies (mAbs) with immune the checkpoint inhibitor anti-CTLA4 mAb will impact tumor progression." (PMID 38891044, 2024). "Consequently, the CD80-CTLA-4 interaction inactivates T cells, while the CD80-CD28 interaction activates T cells, resulting in a more potent and sustained immune response against tumor cells." (PMID 38999940, 2024). "Furthermore, we assessed immune cell infiltration by quantifying several immune cell types involved in the tumor immune response, including Treg cells (CD4+Foxp3+ T cells), M1 macrophages (CD80+CD11c+ cells), M2 macrophages (CD80+CD206+ cells), PD-1+CD8+ cells, and CD39+CD8+ cells." (PMID 39465257, 2024). "None of the tumor cells were labeled with the anti-CD80 antibody." (PMID 39224452, 2024).
tumor (continued). "Furthermore, the expression of CTLA-4 in the sorted T cells increases slightly in the CAP-treated group, in a manner similar to the expression of its ligand, CD80, in the tumor cells; however, the difference is not significant." (PMID 37189453, 2023). "Interestingly, in our study, the proportion of CD11b−F4/80+ cells in the spleen showed a positive correlation with tumor weight, whereas the proportion of CD86+ cells and CD80+ cells in CD11b−F4/80+ cells showed a negative correlation with tumor weight." (PMID 37553633, 2023). "The expression of PD-L1 on tumor cells contributes to the prediction of clinical efficacy of ICI in some tumor types, such as non-small cell lung cancer, which take advantage of the crucial roles played by the PD-L1/PD-1 and CTLA4/CD80/CD86 axes in the evasion of immune surveillance." (PMID 37893096, 2023). "Furthermore, LPS injection to nude mice without tumour burden induced Gr-1 + CD11b + cell surge and CD11b or CD80 positive cell infiltration into spleen." (PMID 35953652, 2023). "In addition, some tumors prompt regulatory T cells (Tregs) to express CTLA-4, leading to downregulation of CD80/CD86 expression in antigen-presenting cells, resulting in reduced production of cytokines such as interleukin 2, which affects the body’s anti-tumor capacity." (PMID 37622124, 2023). "The flow cytometric results showed that the HRMTF NPs could remarkably increase the proportion of the mature DCs (CD11c+CD80+CD86+) both in the primary tumor (39.01%) and in the distant tumor (41.77%) relative to that in the control group (primary tumor: 15.76%; distant tumor: 20.70%)." (PMID 36930774, 2023). "Our data suggest that more time in the host allows for more tumor growth and more immunoediting (potentially of the tumor cells or of the tumor microenvironment), and thus leads to more difficult to treat tumors (e.g. decreased MHC-I, MHC-II, and CD80/86 expression in large A20 tumors shown here)." (PMID 37016127, 2023). "However, co‐stimulatory molecules like CD80, which are crucial for T cell activation, are often poorly expressed, whereas immunosuppressive molecules such as PDL1 and PDL2 are highly expressed on tumor and microenvironment cells." (PMID 37476068, 2023). "The upregulation of CD1C, CD40, CD80, and CD86 on Bregs shown in our study indicated that Bregs might exhibit a strong ability of antigen presentation in the MPE immune microenvironment in vivo due to tumor antigen stimulation." (PMID 37432957, 2023). "Furthermore, tumor cells do not themselves trigger cis-PD-L1/CD80 interactions which result in survival of tumor cells through PD-1/PD-L1 interactions." (PMID 36892732, 2023). "As costimulatory molecules, levels of CD80 and CD86 of DC2.4 in the LEH-CSPC + laser group showed significant enhancements compared with those of LEH-CSPC alone, indicating the importance of the PDT effect on antigen release from tumor cells and subsequent DC maturation." (PMID 37223478, 2023). "However, this evidence suggests that anti-tumor activity induced by anti-CTLA-4 is not mediated by inhibiting CD80/86-CTLA-4 interactions." (PMID 35326731, 2022). "At the same time, cytotoxic T lymphocytes proliferated, DC activation and maturation occurred, co-stimulatory CD80 and 86 surface molecules were upregulated, immunosuppressive cells such as Tregs were reduced, and the TME was significantly improved and promoted the apoptosis of tumor cells." (PMID 36466838, 2022). "Tumor-derived exosomes could restrain DC maturation, down-regulate the expression of surface markers like CD80, CD86, and MHC-II, and up-regulate the expression of CD11b and PD-L1, which ultimately obstructed the anti-tumor activity of Teff and reinforced immune evasion." (PMID 36335094, 2022). "The LC4 peptide was modified to improve its tumour-targeting ability and reduce peripheral immune system activation, which was obtained through phage display peptide library screening and could block the CTLA-4/CD80 interaction." (PMID 36195696, 2022).
tumor (continued). "According to these studies, CD80-Fc may even be effective in treating anti-PD-1 or anti-CTLA-4 -resistant patients and in our study its combination with 4-1BBL-Fc enhanced immune response against tumor cells." (PMID 36480493, 2022). "This study suggested that this tumour infiltration with CD4+ T cells occurred via CTLA-4 expressed on regulatory T cells interacting with CD80-expressing dendritic cells present in peritumoral lymph nodes, thus demonstrating a role for CTLA-4/CD80 interaction in T-cell exclusion." (PMID 35626020, 2022). "CD8+ cells had an anti-tumor effect regardless of CD80 expression on tumor cells." (PMID 33923750, 2021). "Furthermore, our data suggest that it is possible that CD80, CD86, and the CTLA-4-dependent tumor immune escape is involved in the development of tumor aggressiveness, a hypothesis that also merits further study." (PMID 34745002, 2021). "Furthermore, CD4+ cells became pro-tumorigenic in TC-1/dCD80-1-induced tumors, while CD8+ cells controlled tumor growth regardless of CD80 expression." (PMID 33923750, 2021). "The PD-1/PD-L1 pathway regulates T cell activation during inflammatory processes, while CTLA-4 is a protein receptor on T cell surface, inhibiting T cell activity during the priming phase; miR-424 may inhibit the PD1/PD-L1 and CD80/CTLA-4 activity, inducing tumor suppression." (PMID 34830196, 2021). "The specific markers that we analyzed include tumor stem cell markers (CD24, CD44), markers of immunosuppression (CD47, PD-L1), markers of cell adhesion (CD49d, ICAM-1), markers of lymphocytes co-stimulation (CD80, CD86), and markers of antigen presentation (MHC class I, MHC class II)." (PMID 34411144, 2021). "This corresponds to our previous observation showing that deactivation of PD-L1 in the TC-1 cell line markedly reduced the tumorigenicity of these cells, which implies the pro-tumorigenic role of the PD-L1 molecule, rather than CD80/PD-L1-mediated tumor suppression." (PMID 33923750, 2021). "Our attempts to simulate CRC treatment-induced global activation of T cells by stimulating T cells with microbeads, supported concurrent upregulation of CD80 and PD-L1 on APCs, regardless of whether they were from colon, tumor or blood." (PMID 34680397, 2021). "On the other hand, the abundance of intratumoral CD80+ APCs might represent a persistent tumor infiltration of circulating APCs that upregulate CD80 as they enter the non-sterile tumor environment." (PMID 34680397, 2021). "Furthermore, when stimulated by tumor antigens, γδ T cells will up-regulate the expression of antigen-presenting molecules HLA-DR, costimulatory and adhesion molecules (CD80, CD86, CD40) and scavenger receptor CD36, which allow γδ T cells to participate in the elimination of tumor cells." (PMID 32413966, 2020). "Indeed, ID-1 has a similar effect of apoptosis induction exerted on the CD-80 and CD-86 ligands on these tumor cells (data not shown), accordingly with previous results reported in literature." (PMID 32781690, 2020). "However, the cell surface-expressed CD80 may be reduced in CRC cells, thereby leading to immunosurveillance escape of these tumor cells in the TME." (PMID 33419310, 2020). "CD80 has been shown to interact with PD-L1/CD274 in cis on antigen-presenting cells to disrupt PD-L1/PD1 binding, and CD80 expression might differ between antigen-presenting cells in blood and tumor tissue." (PMID 33066260, 2020). "Importantly, expression of CD80 and CD86 on monocultured DCs treated with the chemotherapeutic agents did not significantly differ from vehicle, indicating that the immunogenic effects of chemotherapy rely on their interaction with tumor cells." (PMID 32560232, 2020). "CARTs were employed to deliver mRNA for CD70, OX40L, CD80, and CD86 (co-stimulatory proteins for T-cells), as well as IL-12 and IFN-γ (cytokines that enhance Th1 tumoricidal response) to macrophages in murine subcutaneous models of two tumors, where only one tumor was treated." (PMID 33050070, 2020).
tumor (continued). "Furthermore, the expression levels of co-stimulatory molecules, including CD80, CD86, and I-ab, were higher on tumor-infiltrating DCs from lent-miR-138-5p treated mice compared with other groups, indicating enhanced maturity of tumor-infiltrating DCs from lent-miR-138-5p treated A549 bearing mice." (PMID 32754587, 2020). "Ipilimumab binds to CTLA-4 on T-cells, which inhibits its ability to bind to CD80/CD86, allowing for the expansion of a repertoire of antigen-specific anti-tumor cytotoxic CD8+ T-cells and CD4+ T-cells, which corresponds to an improved anti-tumor immune response." (PMID 33256089, 2020). "However, considering the expression of CD80 and CD86 on APCs, using these receptors might induce an untimely immune reaction against the HAdV, preventing infection of tumor cells in the TME." (PMID 32957644, 2020). "Since our results indicate that H-1299 tumor cells downregulate the expression of CD40, CD80, CD86, and HLA-DR on CD1c+ DCs isolated from healthy donors, we proposed that H-1299 cells may also block the expression of costimulatory molecules on CD1c+ DCs derived from NSCLC patients." (PMID 31921114, 2019). "Besides, CD80 and CD86 in the body can enhance the immune response of cells in vivo to tumor cells." (PMID 31223571, 2019). "These immune checkpoint inhibitor therapies restore anti-tumor immune responses by disrupting the interactions between receptors (PD-1 or CTLA-4) on T and NK cells and their corresponding ligands, PD-L1 on tumor cells or CD80/86 on antigen presenting cells, respectively." (PMID 30941308, 2019). "CD80 and CD86 are also widely expressed in the hematological tumor microenvironment, and studies have shown that deletion of these genes may lead to failure of anti-tumor treatments." (PMID 31195368, 2019). "In similar fashion within the confines of the tumour, CTLA-4 fosters immunosuppression through the induction and differentiation of Treg cells along with the upregulation of IL-10 and IDO (indoleamine-2,3-dioxygenase) by means of a CD80 and CD86 counter signaling approach." (PMID 30893948, 2019). "Furthermore, we found that the expression of PD-L2, CD80, CD86, and CTLA-4 are also elevated in cytomegalovirus and EBV-positive tumor patients, suggesting anti-PD-L2 and anti-CTLA4 immunotherapy may be effective in patients with these types of tumors." (PMID 30911684, 2019). "Additionally, the tumor specific DCs activate Th cells through the interactions between TCRs and MHC class II-antigen complexes as well as the binding between their costimulatory molecules, such as the binding between CD80/CD86 and CD28." (PMID 30740111, 2018). "Thus, consistent with the Raji in vitro studies above, T cells engineered with AbTCR reduce cytokine release without a loss of anti-tumor activity, in a PDX tumor model that lacks CD80 and CD86 costimulation." (PMID 30479831, 2018). "Furthermore, we show reduced expression of T cell co-stimulatory molecules, such as CD80 and CD86, in GBC-PC, supporting an immunosuppressive phenotype that might prevent tumor clearance." (PMID 28978142, 2017). "However, this was demonstrated to be unlikely, as we found that CD80-transfected 4T1.2/HER2 cells behaved similarly to wild type 4T1.2/HER2 cells (without CD80) in terms of tumor regression." (PMID 28460461, 2017). "Tumor cells increase the surface expression of immunogenic molecules, including adhesion molecules, death receptors, stress-induced ligands, cryptic antigens, and stimulatory molecules, such as MHC-I and CD80, thereby becoming more sensitive to T cell-mediated cytotoxicity." (PMID 28337197, 2017). "IEC isolated from patients with non neoplastic disease provoked an increase in the proportion of activated CD8+CD38+ T-cell that was significantly blocked by the addition of anti-CD80 antibody, whereas no significant changes were observed in terms of CD4 activation." (PMID 25595911, 2015).
tumor (continued). "Thus, the CD19-driven CD28 signal given in the absence of CD80 molecules is sufficient to trigger T-cell sustained proliferation and anti-tumor activity, which are unaffected by CTLA-4 inhibition." (PMID 26110267, 2015). "Importantly, this also suggests that measuring the expression of Fas, CD80 and CD86 in patient tumor samples may be used as a biomarker for patient that might benefit from this treatment." (PMID 25227919, 2014). "In addition, cancer cells do not normally express key co-stimulatory molecules such as CD80, but rather express some co-inhibitory molecules that render tumor antigen specific T cell tolerance." (PMID 23671644, 2013). "This suggested that CD86, but not CD80, might be involved in the CTLA4Ig-mediated anti-tumor activity by regulating NK cell function." (PMID 24349559, 2013). "In MM patients the number of dendritic cells (DCs) is normal, but CD80 (B7-1) expression may fail to be upregulated in the presence of trimeric human CD40-ligand (HU-CD40LT) because of the negative effect of tumor-derived TGF-β or IL-10." (PMID 22919394, 2012). "The efficient stimulation of tumor-specific T lymphocytes by DCs requires the presentation of tumor-derived epitopes on MHC class I and II molecules together with second signals (costimulatory molecules CD80, CD86, CD40) and proinflammatory cytokines such as IL-12 or TNF-α." (PMID 22110524, 2011). "However, such an effect was not apparent in our studies, with the moderate increase in CD80 expression combined with GM-CSF through gene transduction sufficient to significantly reduce tumour growth." (PMID 21172020, 2010). "The results of our studies are entirely consistent with the concept that CD80- and CD86-expressing APC play a central role in mediating the immune protection induced by semi-allogeneic vaccines by activating a Th-1 response and instructing T cells responsible for killing autologous tumor cells." (PMID 17686178, 2007). "Moreover, mature DCs (CD45+CD11c+CD80+CD86+) within the tumors were analyzed by flow cytometry after the third treatment, revealing a higher proportion in the MNs (TDEVs@OVs)‐treated group, indicative of enhanced recruitment and maturation of DCs crucial for activating tumor‐specific T cells." (PMID 41496440, 2026). "Furthermore, another study showed that butyrate inhibited the upregulation of CD80/CD86 on dendritic cells and the expression of Inducible T-cell Co-Stimulator on T cells in a mouse model, thereby impairing the recruitment of effector and memory T cells targeting tumor antigens." (PMID 40771692, 2025). "On the basis of our studies, we would predict that blocking CTLA-4 may promote intracellular CD80 and PD-L1 signals that may increase DC migration, and it is possible that in the clinic, this is a mechanism that affects the efficacy of CTLA-4 blockade in a tumor setting." (PMID 39879305, 2025). "Thus, I-sEV PD-1/CD80 plays an intensive role than IFN-γ in muting antitumour immunity, even simultaneous stimulation of tumour cells with sEV PD-1/CD80 and IFN-γ (both at the pathophysiological concentrations in cancer patients), may still lead to cold tumour phenotype." (PMID 38719909, 2024). "We showed that DCIR1 is expressed on tumor-infiltrating myeloid cells but not on T lymphocytes, and that DCIR1 deficiency was associated with a reduced cell surface expression of molecules for antigen presentation in TAMs (notably MHC-I, CD80 and to a lesser extent MHC-II)." (PMID 38532110, 2024). "Based on immunophenotyping tumours, we speculate that this differential effect may, in part, be attributed to the capacity of anti-CTLA-4 blocking the CTLA-4 immunosuppressive properties such as attenuation of CD28 signalling through binding of CD80/8635,52,53." (PMID 39322643, 2024). "Indeed, Raji tumors with CD80/86/70 deletion also rejected in HIS-reconstituted mice, indicating that other factors may contribute to the ability of Raji tumors to elicit tumor-specific T-cell responses in vivo." (PMID 37087494, 2023).